CRP (C-reactive protein)
Diseases named in the same sentence as CRP in open-access papers (continued):
Sharing a sentence is not in itself a finding about the gene and the disease.
Thrombocytopenia (continued). "Low serum lymphocyte levels, low lymphocyte-to-C-reactive protein ratio, low platelet-to-lymphocyte ratio, thrombocytopenia, and high neutrophil-lymphocyte ratio (NLR) have been observed in critical infections." (PMID 36187170, 2022). "In another study conducted with 876 male and 876 female patients, the male patients with more severe COVID-19 infection had higher CRP, troponin, transaminases and ferritin values and more lymphocytopenia and thrombocytopenia." (PMID 36654624, 2022). "Different studies have found a connection between symptoms, including hemoptysis, thrombocytopenia, and high C-reactive protein levels." (PMID 35324813, 2022). "Thrombocytopenia, elevated erythrocyte sedimentation rate, serum C-reactive protein (CRP), and total serum IgG; as well as reduced complement activity were reported." (PMID 35361277, 2022). "Based on the result of univariate analyses, we performed logistic regression analysis to identify the clinical characteristics of older AA patients, which included epigastric pain, thrombocytopenia, and CRP >5 mg/dl as explanatory factors." (PMID 35004106, 2022). "Cirrhosis severity/MELD score, thrombocytopenia (≤50.000 dL−1), inflammation defined as a C-reactive protein concentration > 1.8 mg/dL, and history of SAH were identified as risk factors for one-year hemorrhagic stroke after LT." (PMID 35207251, 2022). "The patients with late development of thrombocytopenia demonstrated higher levels of neutrophil counts at 21–30 days, CRP at 11–20 days and 21–30 days after symptom onset compared with patients with early development of thrombocytopenia." (PMID 35791362, 2022). "Individuals with combined immunodeficiencies with syndromic features had increased odds of positive blood or respiratory cultures, hyperferritinemia, thrombocytopenia, and CRP > 10 mg/dl." (PMID 34973142, 2022). "In blood tests, thrombocytopenia, with a platelet count < 100, 000/mm3, was noted in 12.6% of the patients, whereas increased high-sensitivity C-reactive protein (hs-CRP) levels > 10 mg/dL were identified in 42.8% of the patients." (PMID 33727651, 2021). "CRS is characterized by high fever, thrombocytopenia, hyperferritinemia, as well as increase of inflammatory markers (such as C-reactive protein (CRP))." (PMID 37287491, 2021). "We can only indirectly measure inflammation and hypercoagulability through elevated blood markers for inflammation (like CRP, interleukin 6, ferritin) along with elevated D-Dimers, prolonged prothrombin time, and thrombocytopenia." (PMID 33619668, 2021). "Laboratory analysis revealed a white blood cell count of 1.27 × 104 cells/μL with 84% of neutrophil granulocytes, mild thrombocytopenia (8.6 × 104 cells/μL), and a C-reactive protein level of 16.25 mg/L (reference value <5 mg/L)." (PMID 34413841, 2021). "Patients with MIS-C had more impressive thrombocytopenia and higher levels of CRP, ferritin, ALT, AST, LDH, creatinine, triglycerides, troponin, and D-dimer." (PMID 34858909, 2021). "Leukopenia, elevated c-reactive protein (CRP) levels, thrombocytopenia, and acute kidney injury were common laboratory findings associated with the disease." (PMID 33833931, 2021). "This was predominantly manifested by lymphocytopenia, thrombocytopenia and elevated levels of pro-calcitonin, aspartate and alanine transaminases, total bilirubin, creatinine, C-Reactive protein, serum ferritin and venous lactate." (PMID 33439908, 2021). "An improvement in clinical symptoms was evidenced within 7 days of treatment including fever, dry cough, fatigue and other symptoms such as thrombocytopenia, lymphocytopenia and C-reactive protein." (PMID 34550994, 2021). "ROC curves and AUC values for IL-6, PCT and CRP were calculated with respect to predicting inotropic support need, intubation and thrombocytopenia within 3 days of suspicion." (PMID 33407770, 2021).
Thrombocytopenia (continued). "The main discriminative factors between two diseases are onset age, high CRP, thrombocytopenia, increased D-dimer, and GI involvement." (PMID 34858909, 2021). "An enhanced serum creatinine value (1.6 mg/dL) and impaired (59 mL/min) glomerular filtration rate (GFR), determined using the CKD-EPI method, were noted; thrombocytopenia and an elevated C-reactive protein level persisted." (PMID 33754997, 2021). "The initial laboratory results showed a normal white blood cell count (WBC) of 7500 G/l with lymphocytopenia (9%), thrombocytopenia (149 G/l), and an elevated C-reactive protein (CRP) of 140 mg/l." (PMID 32785885, 2021). "Five criteria, CRP >11 mg/dl (18 points), D-dimer >607 ng/ml (27 points), age >5 years (30 points), thrombocytopenia (25 points), and GI involvement (28 points), were included in the KMDscore." (PMID 34858909, 2021). "We excluded duplicated parameters, and multivariate analysis was allowed to extract five criteria: CRP >11 mg/dl, D-dimer >607 ng/ml, age >5 years, thrombocytopenia, and GI involvement." (PMID 34858909, 2021). "This is in favor of the proposed pathological role of elevated low-level (high-sensitivity) CRP in thrombocytopenia and cardiovascular disease." (PMID 33790888, 2021). "Our patient showed increased erythrocyte sedimentation rate (ESR) and CRP, thrombocytopenia, and leukopenia after surgery." (PMID 34321077, 2021). "Coinfection was confirmed by hepatitis A immunoglobulin M and dengue immunoglobulin M. At the time of diagnosis, white blood cells were normal, with mild neutrophilia and thrombocytopenia along with elevated C-reactive protein." (PMID 34507614, 2021). "The result of laboratory tests showed leukopenia (white blood cell (WBC): 4200/mm3), thrombocytopenia (platelet count: 73,000/mm3), high C-reactive protein (CRP: 43 mg/L), hemoglobinemia (hemoglobin level: 11.2 g/dL), and normal liver function tests." (PMID 33494816, 2021). "Blood testing at the day of admission revealed thrombocytopenia (63 platelets/nL), markedly elevated C-reactive protein (63.6 mg/L), and borderline leukocyte (9.8 cells/nL) and serum creatinine (1.2 mg/dL) values." (PMID 33754997, 2021). "Laboratory findings evaluation revealed that elevated CRP, thrombocytopenia, and increased D-dimer were among the most abnormal laboratory changes." (PMID 33224961, 2020). "Prolonged concurrent mixed presentation of leukopenia, thrombocytopenia and low or normal C-reactive protein (CRP) level is a characteristic finding in severe fever with thrombocytopenia syndrome (SFTS)." (PMID 32134948, 2020). "Laboratory examination of patients showed that elevated C-reactive protein (CRP) (in six studies) and thrombocytopenia (in four studies) were the most common findings." (PMID 33224961, 2020). "The S2 subtype of ‘leukopenia plus normal CRP’ was more common with upper respiratory infection and acute gastroenteritis than were the other S2 subtypes of ‘leukopenia plus thrombocytopenia’ or ‘thrombocytopenia plus normal CRP’ (P <0.001)." (PMID 32134948, 2020). "Animal ID A17230 was found to be both campylobacter and giardia positive at day 5 posttransplant, and euthanasia was elected because of severe thrombocytopenia, acutely elevated C-reactive protein, and blood urea nitrogen, as well as clinical disorientation." (PMID 33134503, 2020). "A computed tomography (CT) scan showed ascites, hepatosplenomegaly, and mildly enlarged multiple lymph nodes, and blood examination revealed renal impairment, thrombocytopenia, and high levels of C-reactive protein (CRP)." (PMID 33489586, 2020). "On laboratory examination, marked thrombocytopenia and elevated creatinine and C-reactive protein levels were present." (PMID 33080751, 2020). "Fatal group had higher rates of ‘leukopenia + thrombocytopenia’ (P <0.001) or ‘thrombocytopenia + increased CRP’ (P = 0.014)." (PMID 32134948, 2020).
Thrombocytopenia (continued). "The SFTS prediction score ranged from 0 to 3 according to the concurrent presence of leukopenia (white blood cell count <4,000 /mm3), thrombocytopenia (platelet count <80,000 /mm3) and normal CRP (<1 mg/dL)." (PMID 32134948, 2020). "The fatal group also had a higher rate of ‘leukopenia + thrombocytopenia + increased CRP’ (P = 0.044)." (PMID 32134948, 2020). "‘Thrombocytopenia plus normal CRP’ was zero from D1 to D4 and then gradually increased and peaked at D12, reaching zero again after D14." (PMID 32134948, 2020). "On the second admission, laboratory tests showed thrombocytopenia (24 × 103/μL), microcytic anemia (hemoglobin, 9.6 g/dL), and slightly elevated CRP level (0.61 mg/dL)." (PMID 33080751, 2020). "Her admission laboratory tests showed leukopenia and thrombocytopenia, accompanied by elevated CRP and lactate dehydrogenase levels." (PMID 32430957, 2020). "One study used three variables to generate a prediction score: leukopenia (WBC count < 4000/mm3), thrombocytopenia (platelet count < 80,000/mm3), and a low CRP level (<1 mg/dL)." (PMID 33374620, 2020). "In case of S2, ‘leukopenia plus thrombocytopenia’ or ‘leukopenia plus normal CRP’ subtypes were the majority (39.3%–60.0%) from D1 to D4, but ‘leukopenia plus thrombocytopenia’ was dominant from D5 to D9." (PMID 32134948, 2020). "Her clinical presentation (thrombocytopenia, anasarca, fever, elevated CRP and creatinine level, hepato-splenomegaly, and lymphadenopathy) and the histological findings of the axillary lymph node were compatible with TAFRO syndrome." (PMID 33080751, 2020). "Leukopenia, thrombocytopenia, and low CRP level are well known manifestations in SFTS, but it is not known how these parameters interact and what is their relationship with other febrile diseases." (PMID 32134948, 2020). "General laboratory findings included elevated CRP values, to a lesser extent thrombocytopenia, and elevated bilirubin, LDH, and kidney function." (PMID 32102367, 2020). "Total leukocyte count (<4000/ mm3), absolute neutrophil count (<1800/mm3), C-reactive protein (>6), thrombocytopenia (<150000/ mm3), and hypoglycemia (<40 mg/dl) was recorded in 3 (3.9%), 7 (9.1%), 55 (71.4%), 35 (45.5%), and 8 (10.4%) respectively." (PMID 34506425, 2020). "Most patients had fever and headache, and laboratory test results included elevated C-reactive protein, thrombocytopenia, and neutrophilia." (PMID 32308194, 2020). "Some studies compared SFTS and scrub typhus; one of these studies explored the prediction score generated from three variables, namely leukopenia, thrombocytopenia, and low C-reactive protein, with a high sensitivity of 93.1% and specificity of 96.1%." (PMID 33374620, 2020). "The serial temporal changes in leukopenia, thrombocytopenia and normal CRP level were followed in reference to the onset of illness." (PMID 32134948, 2020). "In blood tests, he had thrombocytopenia, C-reactive protein (CRP) was elevated, and he had hyponatremia disturbance in liver function." (PMID 33302479, 2020). "Giant basophilic lymphocytes are detected in the blood, thrombocytopenia is possible, and high C-reactive protein (CRP) values are registered; an increase in hepatic transaminases levels is found in some patients." (PMID 32708482, 2020). "In this study, we analyzed the dynamics of these 3 parameters, leukopenia, thrombocytopenia and normal CRP level, alone or in combination in patients with SFTS." (PMID 32134948, 2020). "SFTS symptoms reported in previous studies included fever and gastrointestinal symptoms, alongside regional lymphadenopathy, leukocytopenia, thrombocytopenia, and low CRP levels." (PMID 33374620, 2020). "Leukopenia, thrombocytopenia and low CRP value are prominent features from the beginning of illness, and these are persistent until second week." (PMID 32134948, 2020).
Thrombocytopenia (continued). "We suggested a clinical prediction scoring tool for SFTS in comparison with scrub typhus that consists of 3 variables: leukopenia (WBC count < 4000/mm3), thrombocytopenia (platelet count < 80,000/mm3) and low CRP (< 1 mg/dL)." (PMID 30782137, 2019). "Patients requiring ICU care were older, had more profound thrombocytopenia, greater liver function test derangement, greater renal impairment, a higher C-reactive protein (CRP) and more likely to have an abnormal CXR." (PMID 31318873, 2019). "A chest X-ray was negative and laboratory examinations were unremarkable except for an increase of C reactive protein (50.9 mg/L) and mild thrombocytopaenia (153,000/μL)." (PMID 31088460, 2019). "Initial investigations revealed neutrophilia with normal white blood cell count, thrombocytopenia, elevated blood urea, serum creatinine, C-reactive protein and AST." (PMID 30885170, 2019). "Initial investigations revealed neutrophil leukocytosis with thrombocytopenia, high C-reactive protein level, high serum creatinine with marginally elevated liver transaminases (AST > ALT)." (PMID 30885170, 2019). "His liver transaminases, serum creatine, blood urea, C-reactive protein, and neutrophil percentage were high, and thrombocytopenia was present." (PMID 31360559, 2019). "Initial laboratory work up showed neutrophilia with normal white cell count, thrombocytopenia, high C-reactive protein (250 mg/L), high serum creatinine (146 micromol/L) and normal liver transaminases." (PMID 30885170, 2019). "On the 4th day of life (4/19/2017), phototherapy for jaundice was implemented, and repeat laboratory testing revealed neutropenia and thrombocytopenia with elevated C-reactive protein (CRP)." (PMID 30012112, 2018). "He returned to the neonatal ICU on 04/21/17 due to worsening thrombocytopenia, a significant increase in CRP, tachycardia, hyperthermia and mild respiratory distress." (PMID 30012112, 2018). "Leukopenia, thrombocytopenia, and C reactive protein (CRP) were observed in 66.67%, 92.31%, and 79.49% of cases respectively." (PMID 30234071, 2018). "Investigations showed a leukocyte count of 10,000/μl with thrombocytopenia (platelet count of 117,000/μl) and elevated C reactive protein (CRP)." (PMID 29121980, 2017). "There also were high percentages of patients with clinical evidence of leukopenia, thrombocytopenia, and elevated liver enzymes, and 100% of 25 patients evaluated had elevated concentrations of serum C-reactive protein at the time of presentation." (PMID 28628633, 2017). "We found that leukopenia, thrombocytopenia and high CRP level were significant predictors for mortality." (PMID 28149700, 2017). "Based on the finding of our study, we suggest an aggressive antibiotic treatment and early surgical intervention if needed in patients with leukopenia, thrombocytopenia and elevated CRP level at admission." (PMID 28149700, 2017). "She improved clinically, but thrombocytopenia persisted and her C-reactive protein (CRP) level was high." (PMID 27834717, 2016). "WBC count and CRP are important indicators of the inflammatory response, while thrombocytopenia is a sign for severe infection." (PMID 27375739, 2016). "Other laboratory examinations showed a tendency towardleucopoenia, with mild thrombocytopaenia and enhanced CRP (227.5 mg/dL)." (PMID 27982303, 2016). "Meanwhile, the likelihood of abnormal WBC count, thrombocytopenia, and elevated CRP was significantly higher in the perforated NEC group compared to nonperforated NEC group." (PMID 27375739, 2016). "Laboratory findings showed thrombocytopaenia at 38,000/mm3, leukocytopaenia at 3,800/mm3, C reactive protein at 220 mg/l and slightly elevated liver enzymes (ALAT 68UI/L, ASAT 62UI/L)." (PMID 25626591, 2015). "Most frequent blood test abnormalities were C-reactive protein, lactatedehydrogenase, aspartate aminotransferase and alaninetransaminase elevations and thrombocytopenia." (PMID 26090319, 2015).
Thrombocytopenia (continued). "At admittance, the patient presented dehydration, hepatosplenomegaly, thrombocytopenia, elevated bilirubin, CRP, and D-dimer concentration." (PMID 26451382, 2015). "On 13 July, laboratory tests revealed thrombocytopaenia (26,000/mm3), leukocytes 4,600/mm3, C reactive protein at 163 mg/l, and abnormal liver function transaminase (ALAT 79UI/L, ASAT 50UI/L)." (PMID 25626591, 2015). "First, tachycardia, age, thrombocytopenia and hematocrit have a very low weight (1 to 2) in the score compared to the CRP level that is affected by a weight of +9, which is very close to the cut-off." (PMID 24069477, 2013). "Septic shock and thrombocytopenia at the time of presentation as well as an elevated CRP level were all indicators of the severity of MRSA BSIs." (PMID 23601053, 2013). "Leukopenia, thrombocytopenia, elevated aminotransferases, low CRP and prolonged aPTT, were useful predictive markers for early diagnosis of dengue infection during a large outbreak in southern Taiwan." (PMID 24138072, 2013). "Inflammation is indicated by elevated or decreased blood neutrophils, increased levels of immature neutrophils, thrombocytopaenia and elevated circulating C-reactive protein." (PMID 23742651, 2013). "The most notable laboratory findings included leukopenia, thrombocytopenia, prolonged aPTT, elevated serum levels of aminotransferase and low CRP." (PMID 24138072, 2013). "Platelet counts at days 10 and 14, number of days to reach critical platelet values, duration of thrombocytopenia, neutrophil stress response at 3 hours and count at 14 days, and CRP-to-platelet ratio were correlated with survival." (PMID 21969873, 2011). "Procalcitonin and C-reactive protein (CRP) were markedly elevated, and the patient showed a severe thrombocytopenia." (PMID 20181174, 2009). "Routine laboratory tests showed leukopenia, thrombocytopenia, abnormal liver function test results, elevated concentration of serum C-reactive protein, and elevated procalcitonin levels." (PMID 15757574, 2005). "Therefore, when candidemia is suspected in the neonatal population, the use of predictors such as thrombocytopenia and elevated C-reactive protein has been recommended for the diagnosis of candidemia." (PMID 40872317, 2025). "Conversely, the inflammatory and infectious markers identified include elevated WBC counts, thrombocytopenia, significantly elevated CRP levels, positive urine WBC counts, urine nitrite positivity, lower CT attenuation values of calculi, and higher CT attenuation values of hydronephrosis." (PMID 40361922, 2025). "Laboratory tests revealed hemoglobin 81 g/L, leukopenia (WBC 2.0 × 109/L), thrombocytopenia (platelets 133 × 109/L), reticulocyte 2.21%, elevated C-reactive protein (CRP 14.3 mg/L), erythrocyte sedimentation rate (ESR) increased to 74 mm/h, and a negative Coombs test." (PMID 40831797, 2025). "Rickettsiosis patients, who often present with high-grade fever, rash, headache, hyponatremia, elevated CRP levels, and thrombocytopenia, may benefit from the prompt initiation of doxycycline." (PMID 40094918, 2025). "Furthermore, patients with FPIES usually have less leukopenia and thrombocytopenia, more eosinophilia, and are less likely to have an elevated CRP." (PMID 40217910, 2025). "Key diagnostic clues, such as thrombocytopenia, elevated transaminases and LDH, and characteristically a slight elevation of serum CRP levels, appear instrumental in differentiating SFTS from bacterial sepsis or rickettsial infections in febrile patients with nonspecific presentations." (PMID 41143065, 2025). "Laboratory findings such as leukopenia, thrombocytopenia, elevated CRP, mildly increased procalcitonin, and, less commonly, elevated liver enzymes or acute kidney injury may further support the diagnosis of murine typhus." (PMID 40864107, 2025). "Initial laboratory tests revealed thrombocytopenia and increased C-reactive protein (CRP) level." (PMID 39318635, 2024).